CDK7 (cyclin dependent kinase 7)
Diseases named in the same sentence as CDK7 in open-access papers (continued):
Sharing a sentence is not in itself a finding about the gene and the disease.
tumor (135 papers, 2011 to 2025). "CDK7 inhibition disrupts SE-associated transcription, which is essential for maintaining tumor cell growth and stemness." (PMID 40565099, 2025). "Investigations into the molecular mechanisms underlying anti-tumor effects of targeting CDK7 have primarily implicated its role in cell cycle arrest and the suppression of CDK7-dependent gene transcription." (PMID 38605321, 2024). "Transcriptional activators (such as BRD4 and CDK7) are highly enriched in oncogenic SE regions, and their inhibition preferentially affects SE-associated genes in tumor cells." (PMID 36720920, 2023). "With regard to other pediatric tumors, CDK7 has been shown to be upregulated in a panel of OS cell lines and tumor samples, being associated with worse prognosis and higher metastasis rates." (PMID 36839989, 2023). "A previous study showed that the SE regulator CDK7 inhibitor THZ1 caused significant tumor regression in MYCN-amplified neuroblastoma cells and affected RUNX1 transcription in Jurkat T-ALL cells." (PMID 37501079, 2023). "In line with a tumour-promoting role in CRPC, high tumour CDK7 protein levels are associated with faster biochemical recurrence, marked by rises in serum prostate-specific antigen (PSA)." (PMID 37076563, 2023). "We focused on the relationships between the expression level of CDK7 and clinicopathological characteristics, including sex, age, tumour size, mitotic index and risk category." (PMID 36076237, 2022). "In ESCC, an immunohistochemical (IHC) analysis demonstrated that elevated expression of CDK7 was observed in over 80% samples which was associated with high tumor grade and poor prognosis." (PMID 36387198, 2022). "To further explore the therapeutic potential of SE-driven transcriptional dependencies in G3-MB, we evaluated the inhibitory effects of targeting SE complex components (BRD4 or CDK7) in combination with targeting SE-associated tumor-dependent effector genes." (PMID 36273157, 2022). "It has been reported that triptolide can degrade TFIIH in a CDK7-dependent manner, thereby causing tumor cell death." (PMID 34158845, 2021). "A recent systematic drug sensitivity screening shows that loss of SETD2 sensitized tumor cells to CDK7 inhibitor, and BAP1 depletion confers vulnerability to inhibitor of DNMT150." (PMID 33423045, 2021). "Here, we found that expression of cyclin-dependent kinase 7 (CDK7) was significantly associated with higher tumor grade and worse prognosis in 96 ICC specimens." (PMID 32174795, 2020). "By defining high CDK7 expression and low tumor-infiltrating lymphocyte (TIL) score as two risk factors, patients in cohort II were stratified into three risk groups with different survival outcomes." (PMID 32690037, 2020). "Nevertheless, the underlying mechanism involved in CDK7-induced antiangiogenesis and tumor inhibition of RCC should be further studied." (PMID 31752390, 2019). "CDK7 inhibition was shown to suppress SE-linked gene transcription in a number of tumours." (PMID 38542080, 2024). "stated that overexpression of CDK7 was significantly associated with worse tumor grade (p<0.01)." (PMID 36212402, 2022). "Additionally, elevated expression of CDK7 was positively associated with tumor grade and the poor prognosis." (PMID 34741018, 2021). "Cdk7 levels, however, are higher in many tumor-derived human cell lines, and the selective Cdk7 inhibitor samuraciclib is currently evaluated in several clinical trials (NCT05963997, NCT05963984, NCT06125522)." (PMID 40358525, 2025). "Reprogramming of tumor cells towards kinases such as EGFR, CDK2, and CDK7 has been implicated in resistance to the CDK4/6i palbociclib in ER-positive breast cancer." (PMID 40949156, 2025). "We next examined the effects of both genetic and pharmacological inhibition of CDK7 on tumor growth in vivo." (PMID 41193441, 2025).
tumor (continued). "Treatment with YKL-5-124 or samuraciclib led to significant tumor growth suppression, supporting both the efficacy and safety of CDK7-targeted therapy in clinically relevant models." (PMID 41193441, 2025). "Deletion of CDK7 dramatically impaired the tumor growth of FaDu and HCA-LSC1 cell lines subcutaneously injected in immunodeficient mice, reaching final tumor volume reductions of 60 and 75% respectively." (PMID 41193441, 2025). "Genetic and pharmacological inhibition of CDK7 significantly and consistently reduced tumor cell proliferation due to generalized cell cycle arrest and apoptosis induction." (PMID 41193441, 2025). "Tumor cells were found to be highly reliant on transcriptional machinery, with CDK7 mediating this addiction to a critical cluster of genes in TNBC." (PMID 38605321, 2024). "In the current study, we confirmed that pcamiR1 and its analogue are efficient in regulating CDK7 expression, which indicates that anti-tumor drugs designed by noncoding RNAs have great potential." (PMID 38640110, 2024). "Such targeted delivery system ensures high specificity and efficiency in silencing CDK7, effectively inhibiting tumor growth and progression." (PMID 39209834, 2024). "Results of whole‐genome CRISPR screening from the DepMap project demonstrated strong tumor dependency of CDK7 in all tested GBC lines disregarding the expression levels of SOX9 and TCF7L2." (PMID 39492805, 2024). "The novel insights into the CDK7-CtBP2 axis provide a foundation for exploring this pathway as a potential anti-tumor strategy in TNBC." (PMID 38605321, 2024). "For example, CDK4, CDK6, and CDK7 can influence immunotherapy efficacy by affecting the tumor microenvironment (TME)." (PMID 39371450, 2024). "Nanoparticles, like gold nanoparticles conjugated with internalizing-RGD (iRGD), can be engineered to deliver siRNA targeting CDK7 (siCDK7) directly to the tumor microenvironment." (PMID 39209834, 2024). "In combination treatment with bisphosphonate zoledronic acid, or a CDK7 inhibitor, palbociclib was insufficient in preventing tumour growth." (PMID 37190140, 2023). "CDK7 is an attractive target for inhibitors that kill tumor cells by exploiting high cell proliferation and tumor-specific transcriptional dependencies of oncogenes." (PMID 37507802, 2023). "Targeting SE-associated oncogenic transcription programs by a small-molecule CDK7 inhibitor shows powerful antineoplastic properties against tumor cells." (PMID 37385987, 2023). "In dose escalation, one partial response (PR) is identified with disease control rate of 53% (19/36) and reduction of phosphorylated RNA polymerase II, a substrate of CDK7, in circulating lymphocytes and tumor tissue." (PMID 37488191, 2023). "Targeting essential components of super-enhancers, such as BRD4 and CDK7, has been shown to result in potent anti-tumor effects in preclinical and clinical studies." (PMID 37460542, 2023). "Pre-clinical studies have demonstrated the anti-tumor activity of selective inhibitors of CDK7, including samuraciclib." (PMID 37488191, 2023). "These inhibitors covalently bind to CDK7 outside of the kinase domain and have shown excellent anti-tumor activity by exploiting the transcriptional vulnerability of oncogenes and cell cycle proteins in diverse cancer types." (PMID 37507802, 2023). "To inhibit CDK7 expression in tumors, we synthesized a tumor‐targeted AuNPs system to deliver siRNA." (PMID 37476070, 2023). "We found that high levels of CDK7 in patients’ tumor tissue point to lower survival and disease-free survival rates." (PMID 35158760, 2022). "We compared CDK7 expression in different tumor tissues of the PTs, LNs, DMs, and RDs to verify if expression changes occur during tumor progression." (PMID 35158760, 2022). "The authors suggest that CDK7 inhibition sensitizes tumor cells to therapy with immune checkpoint inhibitors." (PMID 35158760, 2022).
tumor (continued). "Expression pattern for CDK7 between the cores originating from one tumor sample was homogenous meaning that the intratumoral difference in expression of the cells was neglectable." (PMID 36212402, 2022). "Consistent with this, we validated with tissue microarrays (TMAs) that CDK7 overexpression in GISTs was correlated with tumour progression and an unfavourable prognosis." (PMID 36076237, 2022). "We here examined the therapeutic impact of CDK7 inhibition in a preclinical PDAC tumor model and discovered that targeting CDK7 provides a new option to enhance the efficacy of chemotherapy." (PMID 35945614, 2022). "Our previous studies using these inhibitors demonstrated control of mRNA synthesis, cell cycle progression and survival by CDK7 in different tumor cell lines." (PMID 35054996, 2022). "Since THZ1 treatment effectively reduced MYC and inhibited the proliferation as well as induced the apoptosis of the cultured HCC cells, we next assessed in vivo CDK7 inhibition in a mouse HepG2 xenograft tumor model." (PMID 35406486, 2022). "Existing studies have shown that inhibiting CDK7 activity can inhibit transcription and cell cycle progression, thereby inhibiting tumor growth." (PMID 34367944, 2021). "CDK7 inhibitors exert a satisfactory anti-tumor effect on multiple varieties of tumors in vitro and in vivo, which strongly implies that CDK7 inhibition provides a potential clinical application." (PMID 34490348, 2021). "In contrast, specific CDK7/9 targeting of tumor cells improves immune responses and acts synergistic with α-PD1 antibodies." (PMID 33161487, 2021). "If CDK7 activity preferentially affects transcripts necessary for transformed dividing cells, targeting this kinase for anti-tumor therapy can be doubly attractive." (PMID 33805800, 2021). "CDK7 knockout can lead to the exhaustion of adult stem cells, and its inhibition was shown to enhance anti-tumor immunity in small-cell lung cancer (SCLC)." (PMID 33686962, 2021). "Expression of WEE1 (P = .006), CDK6 (P = .02), and CDK7 (P < .001) was enriched in the squamous subtype in both PDCLs and bulk tumor." (PMID 33039466, 2021). "THZ1 is a novel covalent inhibitor of CDK7, which has been shown to be highly effective in killing tumor cells." (PMID 33579893, 2021). "Therapeutically, CDK7 inhibitors have been demonstrated to block tumor growth in patient-derived xenografts of TNBC, given the dependence of a cluster of key genes potentially driven by TNBC-specific SEs30." (PMID 33854062, 2021). "The colony formation assay revealed that CDK7 inhibitors attenuated the tumor stem cell characteristics of MCF-7 cells." (PMID 34490348, 2021). "Pharmacological inhibition of CDK7 by THZ1 rescued the liver overgrowth phenotype caused by MST1 and MST2 double knockout in mice and impeded Yap/Taz-driven tumor cell growth in xenografts." (PMID 33869224, 2021). "CDK7 is a transcription addiction factor that is upregulated in various types of tumor and correlated with prognosis of patients." (PMID 33889549, 2021). "Several studies have reported that aberrant expression of CDK7 has been found in many types of tumor, such as hepatocellular carcinoma, gastric cancer, colorectal cancer, and epithelial ovarian cancer, and correlated with poor prognosis." (PMID 33889549, 2021). "Inhibition of tumour cell transcriptional activity has been also attempted using a covalent inhibitor of CDK7, THZ1." (PMID 34344865, 2021). "Studies have shown that downregulation of Mcl-1 through CDK7 and 2/9 inhibition facilitates the induction of apoptotic cell death in a number of different tumour types." (PMID 34344865, 2021). "THZ1 is a highly specific CDK7 inhibitor that has shown effective anti-tumor activity in small cell lung cancer, ovarian cancer and triple-negative breast cancer." (PMID 34367944, 2021).
tumor (continued). "YKL-5-124 as a single agent and in combination with JQ1, demonstrated near-complete CDK7 engagement in spleen, liver as well as tumor tissues following one-week of treatment." (PMID 35198433, 2021). "Our data showed that CDK7 is highly expressed in NSCLC tumor tissue, and high CDK7 expression is a poor prognostic predictor." (PMID 32690037, 2020). "Combined HER2/CDK7 inhibition resulted in durable tumor regression in the HCC1569 and HCC1954 xenograft tumor models." (PMID 31462705, 2020). "Xenograft studies in mice showed that CDK7 inhibitors are well tolerated and effective at reducing tumour growth in vivo." (PMID 32385714, 2020). "Whilst ABC-transporters can mediate resistance to some CDK7 inhibitors, additional factors that influence tumour response to CDK7 inhibition are yet to be identified." (PMID 32385714, 2020). "Then, we validated the significance of CDK7-dependent regulation of MYC in remodeling tumor immune microenvironment." (PMID 32690037, 2020). "Given the essential roles of CDK7 in regulating the cell cycle and transcription, the outcomes of its specific inhibition in tumor cells by BS-181, including cell cycle arrest and apoptotic cell death, were also expected in rapidly proliferating normal cells." (PMID 33352782, 2020). "Of note, we also found that the PD-L1 protein level correlated with the CDK7 protein level in cohort I and cohort II tumor samples." (PMID 32690037, 2020). "Combined inhibition of HER2 and CDK7 maximally abrogated RNA Pol II activation and induced a durable tumor response." (PMID 31462705, 2020). "The phenotypic changes induced in ICC by CDK7 depletion or THZ1 treatment indicate that CDK7 is involved in cell proliferation, tumor sphere formation, migration, invasion, and cell cycle regulation." (PMID 32174795, 2020). "Given the pivotal role of CDK7 in regulating the expression of genes involved in oncogenesis, stemness, tumor growth, and progression, we next determined the effect of CDK7 inhibition on the expression of MYC, STAT3, and β-catenin." (PMID 32340192, 2020). "Two decades ago, immunohistochemical analyses on a range of tumour types indicated that CDK7 expression is elevated in tumour cells compared with their normal counterparts." (PMID 32385714, 2020). "Together, these data suggest that although CDK7 is a good target to overcome resistance to HER2 therapy in HER2+ BCs, combined inhibition of HER2 and CDK7 offers maximal cell growth inhibition and durable tumor regression." (PMID 31462705, 2020). "CR8 was shown to target similar Cdks as Roscovitine including Cdk1, Cdk2, Cdk5, Cdk7 and Cdk9, but with much stronger efficacy and a predicted improved anti-tumor potential." (PMID 32380742, 2020). "Inhibition of CDK7 reduced tumour cell migration and invasion, as well as tumorsphere formation ability." (PMID 31755214, 2020). "To the best of our knowledge, we are the first to reveal that CDK7 expression is positively correlated with tumor size, TNM stage, and poor prognosis in ICC." (PMID 32174795, 2020). "The CDK7 protein expression was significantly increased in tumor tissues compared with normal bile duct tissues." (PMID 31399555, 2019). "The underlying mechanism involved in CDK7-activated transcription and RCC tumor growth should be further studied." (PMID 31752390, 2019). "Inhibition of BET or CDK7 has been used to target MYC-driven tumours in different contexts, as MYC expression in tumours is frequently maintained at a high level by an associated super-enhancer region." (PMID 29759978, 2018). "CAK-mediated activation of ER drives tumor progression and may enhance the sensitivity of ER + breast cancer to CDK7 inhibition." (PMID 40949156, 2025). "The fusion of IPO11–CDK7 may lead to constitutive activation of CDK7, promoting cell-cycle progression and tumor growth." (PMID 40981433, 2025).
tumor (continued). "However, the compelling immunomodulatory potential inherent in CDK7’s role in the anti-tumor immune response is presently in its nascent stages." (PMID 38605321, 2024). "Most remarkably, the combination of CDK7 inhibitors with known therapeutic agents like fulvestrant or tamoxifen has shown enhanced efficacy in inhibiting tumor growth compared to either single agent, highlighting the potential therapeutic advantage of these combinations." (PMID 38605321, 2024). "Furthermore, CPYPP and curcumin significantly suppressed tumor growth, tumor weight, CDK7, and CDK9 activities in an OECM1-DTX orthotopic mouse model, consistently with upregulated proteasome activity and sustained body weight." (PMID 38858714, 2024). "HSPs, therefore, may serve as functional associated activators with the CDK7/CDK9–Rpb1 complex, akin to TLR4 activation in tumor-induced muscle wasting." (PMID 38858714, 2024). "Additionally, the CDK7/9 inhibitor was shown to inhibit UM tumor growth and liver metastases, highlighting the need for further research on this therapeutic approach." (PMID 39598629, 2024). "Considering that CDK7 dysregulation is correlated with various important diseases, the novel CDK7 regulator identified in this study, pcamiR1, or its analogue may represent an evolutionarily conserved target of new anti-tumor drugs." (PMID 38640110, 2024). "Tumor cells mediated by SEs are susceptible to THZ1, a specific CDK7 inhibitor." (PMID 37501079, 2023). "THZ1, a novel covalent CDK7 inhibitor, has been utilized as an anti-tumor drug." (PMID 37524774, 2023). "We also explored the therapeutic potential of combining CDK7 inhibition with the widely prescribed antiandrogen enzalutamide and found additive tumour growth repression in vivo, likely mediated largely through CT7001’s potent repression of cell cycle progression." (PMID 37076563, 2023). "Furthermore, the blocking of CDK7 has been reported to regulate the onset and intensity of immune-inflammatory responses by activating the tumour immune response and regulating granulocyte apoptosis and cytokine secretion." (PMID 35514959, 2022). "However, since our study is the first to describe this linkage, further research is needed to characterize the tumor microenvironment according to CDK7 expression in HNSCC." (PMID 35158760, 2022). "We could show that the expression of CDK7 and pMED1 are correlated throughout different tumor sites." (PMID 35158760, 2022). "The concomitant transcription regulation of both—cell cycle genes and relevant regulatory factors—may well establish a novel programmatic basis for proliferation control of human tumor cells by CDK7." (PMID 35054996, 2022). "The expression of CDK7 has been identified as a target in HCC tumor tissues." (PMID 35406486, 2022). "Targeting CDK7 induces apoptosis and inhibits the tumor growth of HCC." (PMID 35406486, 2022). "Our results suggest that the inhibition of RARαS77 phosphorylation by either expressing RARαS77A or inhibiting RARα’s phosphokinase CDK7, can bypass RA stimuli to transactivate tumor-suppressive miR-3074-5p and reduce oncogenic DHRS3, thus overcoming the RA-resistance of TNBC." (PMID 33902658, 2021). "THZ1, a covalent CDK7 inhibitor, treats tumor types that are dependent on transcription addiction." (PMID 33889549, 2021). "Finally, we demonstrate that the synergistic cytotoxicity observed in vitro translates into anti-tumor effects in vivo, supporting the therapeutic potential of targeting CDK7 and BRD4 in combination in NB." (PMID 35198433, 2021). "In this study, we investigated whether CDK7 inhibition was an effective anti-tumor option and whether GSDME expression was associated with CDK7 levels." (PMID 34490348, 2021). "Inhibition of CDK7 activity was shown to impair transcription and cell cycle progression, and suppress tumor growth 7, suggesting that CDK7 could serve as a therapeutic target in ICC." (PMID 32174795, 2020).